CD4 (CD4 molecule)
Diseases named in the same sentence as CD4 in open-access papers (continued):
Sharing a sentence is not in itself a finding about the gene and the disease.
tumor (continued). "RNA sequencing and MIF indicated elevated immune activation in the LN-ELN group, characterized by increased CD3+, CD4+, and CD8 + T cells within the tumor microenvironment." (PMID 38872183, 2024). "Diverse anti-tumor immune cells, including plasma B cells, CD8+ T cells, activated memory CD4+ T cells, activated natural killer (NK) cells, M1-like macrophages and activated dendritic cells (DCs) were found highly enriched in the low-risk population." (PMID 38438381, 2024). "The anti-melanoma impact of diosgenin appeared to be dependent more on immunity against tumors than on direct tumor suppressive activity, as demonstrated by the tumor tissues' clear production of IFN-γ and CD4+/CD8+ T-cell infiltration." (PMID 39567970, 2024). "Conversely, CD4+T cells and NKT cells, pivotal in tumor eradication, showcased reduced infiltration in high R3HDM1 tumors, fostering an immunosuppressive tumor backdrop." (PMID 39376739, 2024). "We identified one unique spatial architecture with the presence of CD8+ T cells, CD4+ T cells, and other lymphocytes in the same region that restricted the proximity of CD8+ T cells to tumor cells, eventually leading to a worse prognosis." (PMID 38611111, 2024). "Furthermore, they also demonstrated that the Hsp70-engineered exosomes from these MM cells could be used as a tumor vaccine to induce the maturation of DC and trigger the activation of NK cells, CD4 + Th1, and P1A-specific CD8+CTL, hence resulting in a more potent anti-tumor immunity." (PMID 39598562, 2024). "Salvia miltiorrhiza Bunge (Danshen) extract cryptotanshinone, combined with anti-PD-L1 antibody, can make LLC-bearing mice tumor-free and increase CD45+ leukocytes, CD4+, and CD8+ T cells infiltration in tumors." (PMID 38426097, 2024). "DCP-IL-12/FLT3L dramatically increased tumor infiltration by hematopoietic cells, CD8+ and CD4+ T cells compared to DCPs expressing either cytokine alone." (PMID 37996514, 2024). "Next, Bregs also convert CD4+ T cells into activated Tregs by secreting transforming growth factor-beta (TGF-β), which in turn inhibits T cell proliferation and promotes tumor metastasis." (PMID 38464531, 2024). "Through unsupervised clustering analysis, we identified four unique clusters of CD8+ CAR-T cells, three stable clusters of CD4+ CAR-T cells, and one cluster for tumor cells (cluster 0-KRT18, representing 1.2% of total cells)." (PMID 39657666, 2024). "Similar results were also obtained by immunohistochemical analysis, as HY-oAd+9-ING-41 induced the highest level of CD4+ and CD8+ T-cell recruitment in the tumor (*p < 0.05 or ***p < 0.001 versus HY-oAd or 9-ING-41 monotherapy)." (PMID 38812516, 2024). "The positive correlations were detected between SPOP expression and infiltration levels of CD4+ T cells and CD8+ T cells, implying the key role of SPOP in regulating tumor immunology." (PMID 39074086, 2024). "Tumor-infiltrating lymphocytes (TILs), including CD8+ T cells and CD4+ helper T1 lymphocytes, are related to positive outcomes, whereas CD4+ helper T2 lymphocytes are linked to unfavorable patient survival." (PMID 39087024, 2024). "DCm@NPs can mimic APCs and promote the differentiation of CD4+/CD8+ T cells; Tm@NPs can bind to immunosuppressive molecules (e.g., TGF-β) and PD-L1 on tumor cells, effectively restoring T cells’ cancer-killing capabilities." (PMID 38675192, 2024). "Dendritic cells (DCs) present tumor antigens through MHC‐I and/or MHC‐II to CD8+ T cells and CD4+ T cells, triggering an antitumor response." (PMID 39031507, 2024). "The combined OTX008 and anti-PD-1 treatment also led to a significant increase in tumor-infiltrating CD8+ and CD4+ T cells, whereas intratumoral Treg proportions amongst total CD4+ T cells were reduced." (PMID 38169569, 2024).
tumor (continued). "Collectively, these results confirm that tumours treated with PI3K/mTORi and/or PI3K/mTORi+PD‐1i are enriched for an actively proliferating cytotoxic CD4+ and CD8+ T‐cell population, indicative of an ongoing adaptive anti‐tumour immune response." (PMID 38711203, 2024). "Tumor-infiltrating CD8+ T cells were comparable among groups, while CD4+ T cells were less abundant in KO tumors treated with PD-1 blockade." (PMID 39255035, 2024). "Tumour-infiltrating lymphocytes (TILs) are immune cells, including cytotoxic CD8+ lymphocytes and CD4+ T helper cells, that infiltrate tumour tissues." (PMID 39338198, 2024). "We carried out immunohistochemistry staining in 72 human PAAD tumor tissues to estimate correlation between SPOP and CD4+ T cell as well as CD8+ T cell." (PMID 39074086, 2024). "The majority of CD4+ and CD8+ T cells were located in the outer tumor region, with lower percentages in the border and inner regions." (PMID 38203786, 2024). "Conveniently, this increased activation of APCs drives increased numbers of CD4+ and CD8+ cells, which can be directly analyzed and used as important biomarkers of tumor vaccine effectiveness." (PMID 39682188, 2024). "cDC-1 and cDC-2 in the TME play a critical role in capturing tumor antigens to activate CD8+ and CD4+ effector T-cell responses." (PMID 38533507, 2024). "Several of these chemokines including CCL21 (~224-fold) and CXCL13 (~66-fold) were previously shown to exert immunosuppressive effects by recruiting CD4 and CD8 T cells and DC in the TME, thereby inhibiting tumor progression and metastasis." (PMID 39766038, 2024). "Most current studies focus on CD8 + T cells and tumor-constitutionally expressed MHCI, but the cytotoxic effects of CD4 + T cells and tumor-induced expression of MHCII also deserve our attention." (PMID 38816871, 2024). "To identify the effects of tumor-intrinsic Aurora-A in regulating immune cell populations in the TME, we analyzed overall leukocytes, T cells, CD8+ T cells, and CD4+ T cells in Aurora-A knockdown CT26-derived tumors." (PMID 38291041, 2024). "To confirm the negative correlation of PRMT3 expression with the abundance of tumor-infiltrating CD8+ T cells in the RNA-seq analyses, we performed multiplex immunofluorescence (mIF) staining of PRMT3, CD45, CD4, and CD8 on 20 cases of HCC samples." (PMID 39256398, 2024). "Once the host's immune cells are activated (primarily tumor antigen-specific CD8 + and CD4 + T lymphocytes that are activated and stimulated), they can recognize and destroy tumor cells." (PMID 38654309, 2024). "The prevalence of CD4+CD45+ T cells was unaffected by MerTK inhibition in either tumor, as was the prevalence of CD8+CD45+ T cells in the primary tumor." (PMID 38443968, 2024). "To validate the immunogenicity of our predicted tumor antigens, we used dendritic cells (DCs) electroporated with TOFU mRNA as highly effective APCs, capable of eliciting both CD4 + and CD8 + T-cell responses." (PMID 38268001, 2024). "In a pre-clinical study of squamous cell carcinoma, application of A2AR-blocker, SCH5826, decreased CD4+ T regs and promoted a CD8+ T cell-mediated response that reduced tumor growth." (PMID 38994360, 2024). "Mice were implanted with KPC-derived tumor cells on a single flank, and then treated with a STING agonist, which significantly reduced the tumor burden, increased the CD8+/CD4+ T-cell ratio, and increased CXCR3+ CD8+ T cells in the PDAC TME." (PMID 38339310, 2024). "It is highly expressed on CD4 + T cells, CD8 + T cells, NK cells, and TILs, where it inhibits T cell activation and function through its ligand CD155, contributing to tumor immune evasion." (PMID 39465721, 2024). "Immunohistochemical analysis and multiplex immunofluorescence for CD4, CD8, CD25, FOXP3, and PD‐L1 in the tumor were used to identify multiple tumor‐infiltrating immune cells (TIIC), Tregs, and TC." (PMID 39264227, 2024).
tumor (continued). "The study findings suggest that CD4+ cells are essential to maintain and sustain CD8+ TIL-mediated anti-tumor response." (PMID 38779258, 2024). "They found that the viability of CD4+ T cells in the presence of 90Y-NM600 was enhanced when co-cultured with previously irradiated MOC2 and B16 tumor cells." (PMID 39355211, 2024). "An animal demonstrated that combination therapy with a CD40 agonist resulted in a superior effector response compared to anti-PD-1 monotherapy for CCA, accompanied by an increased presence of CD4+ T and CD8+ T cells in tumor-bearing mice." (PMID 39845973, 2024). "presented tumor grade and stage independent prognostic effect of FOXP3+ regulatory T-cells and CD4+ lymphocytes in 157 extrahepatic and 69 gallbladder CCA." (PMID 38751812, 2024). "All in vivo experiments and imaging to quantitate the amount of CD4+ and CD8+ T-cells in and around the tumor were performed at Crown Bio (UK)." (PMID 38204925, 2024). "The results demonstrated a significant increase in the infiltration of CD4+ T and CD8+ T cells within tumor cells infected with recombinant PRV strains." (PMID 39055561, 2024). "When naïve tumour-specific B cells are the only source of I-E+ APC, very limited proliferation of naïve CD4+ T cells is observed, whereas host I-E+ APCs are potent T cell activators." (PMID 38125720, 2024). "An eleven-marker panel (CD3, CD4, CD8, FOXP3, CD68, arginase-1, CD33, HLA-DR, pan-keratin (PanCK), PD-1, and PD-L1) was used to study the tumor and immune cell compositions." (PMID 38898200, 2024). "The secretion of IFN-I and IL-12 by pDCs facilitates the polarization of CD4+ T cells into Th1 helper T cells, which in turn promotes the accumulation of CD8+ T cells involved in the subsequent anti-tumor response." (PMID 38426090, 2024). "CD3+, CD4+, and CD20+ lymphocytes were expressed in all three prostate regions examined in the study—benign biopsy (BBG), tumor‐adjacent normal glands (TAG), and malignant tumor glands (MTG)." (PMID 38523528, 2024). "The densities of CD3, CD4, CD8 and CD66b-expressing immune cells were analyzed in the tumor tissues." (PMID 38462640, 2024). "In 96% of TGCT patients, the proportion of CD4+ cells exceeded that of CD8+ TIL, with their numbers gradually decreasing from tumor central to peripheral areas, and significantly fewer T cells in tumor-free, contralateral testes." (PMID 38649788, 2024). "Remarkably, the combination therapy significantly increased the infiltration of tumor‐infiltrating CD8 and CD4 cells, indicative of an enhanced immune response against the tumor." (PMID 39297408, 2024). "The efficacy of the combination of T-VEC and trabectedin was dependent on both CD4 and CD8 T cells suggesting that trabectedin treatment augments T cell response in the tumor microenvironment." (PMID 39044819, 2024). "Immunohistochemical results showed fewer CD4+ and CD8+ T cells in the core of Ddr1‐WT tumors compared to tumor margins." (PMID 38953306, 2024). "The IHC images demonstrate the expression of CD4 and CD8 was obviously greater in the RILPL2-high tumor centers than in the RILPL2-low tumor centers." (PMID 39078518, 2024). "Through the utilization of CellChat analysis, we observed that outgoing signals from CXCL10+ M1 macrophages to B cells, CD4+ T cells, CD8+ T cells was noticeably enhanced within the tumor group." (PMID 39170612, 2024). "TDLNs are the primary sites for the development of adaptive antitumor immunity, where activated DCs present tumor-related antigens to CD4+ and CD8+ T cells, leading to cytotoxic T cell activation and tumor clearance." (PMID 39560995, 2024). "Conversely, CD4-LV mediated the exclusive generation of CD4+CAR T cells, which were equally active in eliminating tumor cells." (PMID 39272178, 2024). "As spatial proteomics based in IHC methods such as seqIF retain the best markers for tissue region (PanCK: Tumor, SMA: Stroma, CD31: vessel, etc.)and cell (CD4: t-cell, CD68: Macrophage, CD56: NK cell, etc.)identification." (PMID 38473208, 2024).
tumor (continued). "Upon stimulation, naive T cells differentiate into distinct CD4+ helper and CD8+ cytotoxic T cells, which mediate immunity homeostasis and defend against pathogens or tumours." (PMID 38801402, 2024). "Further analysis shows that the adaptive immunity in this model of mice, such as interleukin 12 (IL - 12), IFN - γ, CD4+, CD8+ T cells, instead of innate immune displayed ability to maintain the balance of the occult tumor cells." (PMID 38464531, 2024). "The IHC staining of the mouse HCC tumors clearly uncovered the profound increase of CD4+ T cell, CD8+ T cell, and NK cell staining within the tumor boundary." (PMID 39388278, 2024). "We further compared the exhaustion scores of CD4+T cells and showed that Treg cells and CXCL13+T cells had higher exhaustion scores in obese tumor samples." (PMID 38311726, 2024). "Negative correlation was found between LOXL1 expression and the infiltration abundance of anti-tumor immune cells such as CD8 + T cell, CD4 + T cell, B cell, and dendritic cell in COAD, BRCA, and HNSC." (PMID 38267662, 2024). "Accordingly, treatment with NP-GSDMA3 and Phe-BF3 resulted in an increase in the CD3+, CD4+, and CD8+ T cells population at the tumor site, along with a decrease in the Foxp3+ Treg population." (PMID 38391959, 2024). "Anti-PD-1 mAb treatment is evaluated in patients to stimulate activation of tumor reactive T cells, however it also stimulates PD1+ CD4+ and CD8+ Tregs resulting in higher Treg suppressive activity and unwanted progression of cancer." (PMID 38512889, 2024). "The BiTE construct has been engineered to exhibit dual binding affinity for EpCAM+ tumor cells and CD3+ T cells, leading to the formation of clusters and subsequent activation of CD4+ and CD8+ T cells alongside with cancer cells." (PMID 38464532, 2024). "Together with the present findings, among CD4+ helper T cell components, activated effector CD25+FOXP3+CD45RA− T cells possibly play crucial roles in tumor chemosensitivity." (PMID 39232704, 2024). "Local intratumoral production of IFN-γ by tumor-infiltrating NK, CD4 Th1, and CD8 cytotoxic T lymphocytes appears to result in the generation of high levels of specific antitumor CTLs, ultimately leading to tumor growth suppression." (PMID 39452870, 2024). "Previous studies have demonstrated that CD4+ and CD8+ T cells suppress HCC development through the induction of anti-tumor immune responses." (PMID 39445019, 2024). "Compared to regulate the macrophages in the microenvironment, Bazhen Decoction (BZD) can increase the ratio of CD4+T cells to CD8+T cells in the spleen and tumor tissues, downregulate the PD-1 expression on T cell surfaces." (PMID 38783955, 2024). "Upon subcutaneous injection of MC-38 cells, tumor antigens can be taken up by DCs and presented to CD4+ and CD8+ T cells in tumor-draining lymph nodes." (PMID 39040850, 2024). "Clinical studies indicate a correlation between CD4, CD8, and macrophage levels in the tumor microenvironment and treatment outcomes." (PMID 39058687, 2024). "BCG triggers the activation of both CD4+ and CD8+ T cells into the bladder wall, eliminating tumor cells and, consequently, decreasing tumor recurrence." (PMID 38339010, 2024). "Our analysis revealed a significant increase of CD4+ and CD8+ T‐cell infiltration in tumours treated with PI3K/mTORi and PI3K/mTORi+PD‐1i, as compared to tumours treated with vehicle or PD‐1i alone." (PMID 38711203, 2024). "Bap1 knockout resulted in a notably decrease in the tumor infiltration of CD45+CD8+ T cells and CD45+CD4+ T cells, while increased the infiltration of repressive CD11b + Gr1 + myeloid cells." (PMID 39350280, 2024). "Further investigations of different T cell subtypes demonstrated that whilst CD4+ and CD8 + T cell infiltration was the same between groups, there were more γδ T cells in Vil Apc Dock2 tumours than control tumours." (PMID 39242821, 2024).
tumor (continued). "Tumor infiltrating immune cell analysis by immunohistochemistry showed no changes in the number of CD163+ M2-like macrophages, CD4+ or B220+ cells in the different therapy groups." (PMID 38824552, 2024). "Upon uptake of the tumor antigen, they can migrate to lymphoid organs and present antigens via MHC I and II to CD8+ and CD4+ T cells." (PMID 38927922, 2024). "The CD4+ T cell subclass, i.e., CD4+ CD25+ Foxp3+ Tregs, plays an important role in the tumor regulation of the immune response." (PMID 39329710, 2024). "Studies on head and neck squamous cell carcinoma and colorectal cancer tumor tissues have revealed that the co-expression of PD-1 and ICOS on solid tumors identifies CD4+ T cells reactive to the tumor." (PMID 38426090, 2024). "For example, in vivo NIR-II structured-illumination light-sheet microscopy (LSM-SIM) can longitudinally map out cellular CD4, CD8 and OX40 expression levels in tumour tissue in response to immunotherapy." (PMID 37620621, 2024). "The addition of R837 as an adjuvant triggers potent ICD, promoting the infiltration of CD4+ and CD8+ T cells and leading to a robust anti-tumor immune response, effectively eliminating primary and metastatic tumors." (PMID 38998669, 2024). "Higher numbers of CD4+ T cells, CD8+ T cells, CD20+ B cells, CD68+ macrophages, LAMP3+ DCs, PD-L1+ cells, and TLSs were detected in patients with a single tumor than in those with multiple tumors." (PMID 38254190, 2024). "Numerous studies have demonstrated the impact of tumor-derived EVs on various immune cell populations, including CD8+ T cells, CD4+ T cells, γδ T cells, macrophages, and MDSCs." (PMID 38816455, 2024). "When CD4+ T lymphocytes encounter MHC class II molecules, they produce IFN-γ, which prompts host cells to eliminate tumor cells." (PMID 39452154, 2024). "Immunogenic cell death, maturation and activation of DCs (CD11c+, CD11c+CD86+, CD11c+MHC-I+), cytotoxic T-lymphocyte anti-tumor immune effects (CD3+, CD3+CD4+ and CD3+CD8+), increased stimulating the transition of T cells to Th1 phenotype." (PMID 38791452, 2024). "For example, CD4+ T cells are more frequently located in the periphery of the tumor, whereas CD8+ TILs usually concentrate in the inner regions of the tumor." (PMID 39456636, 2024). "The inhibition of SLC7A5 leads to the enhancement of CD4+ and CD8+ T lymphocytes, thereby boosting the immune response while concurrently diminishing tumor progression and cellular migration." (PMID 38397971, 2024). "For lymphoid populations, there was a trend of an increase in number of tumour infiltrating lymphocytes (CD3+ T, CD4+ T, CD8+ T, and B cells) per gram of tumour, although the CD8+ T cells had a comparable frequency of memory cells in both treatment groups." (PMID 38554167, 2024). "Regulatory T cells (Tregs), a major subset of T cells involved in immune suppression, suppressed the antitumor activity of CD4+ T cells and CD8+ T cells in the tumor immune microenvironment." (PMID 38254219, 2024). "Our results demonstrated that cell cycle inhibitors recruited cytotoxic immune cells, including CD4+ T cells, CD8+ T cells, and NK cells, to infiltrate into the tumor core." (PMID 39388278, 2024). "As expected, quantitative flow cytometry analysis revealed a significant increase in the infiltration of CD3+, CD4+, and CD8+ T cells at the 4T1 tumor site due to IR‐LND@Lip treatment." (PMID 38704675, 2024). "On the other hand, CD4+ T-helper and MHC2+ cells were decreased in male mice, suggesting reduced immune activation and, thus, inefficient tumor surveillance, which encourages secondary colonization." (PMID 39684829, 2024). "In PDAC, high CD73 expression is associated with an immunosuppressive TME, decreased survival rates, and reduced levels of CD4+, CD8+, and CD21+ tumor-infiltrating lymphocytes (TILs)." (PMID 39682280, 2024). "IL-17A indirectly attracts CD4+ and CD8+ T cells to tumor sites and enhances natural killer cell activity." (PMID 39411241, 2024).